CRP (C-reactive protein)
Diseases named in the same sentence as CRP in open-access papers (continued):
Sharing a sentence is not in itself a finding about the gene and the disease.
infection (continued). "Nine studies reported the prevalence of low-grade inflammation after excluding participants with suspected infection, defined as CRP >10 mg/L." (PMID 31258105, 2019). "The neutrophil/lymphocyte ratio is a better addition to C-reactive protein than CD64 index as a marker for infection in COPD." (PMID 31015366, 2019). "The sensitivity and specificity of PCT and CRP for predicting infection were calculated using a receiver operating characteristic (ROC) curve." (PMID 31691767, 2019). "Elevated concentrations of C-reactive protein or other markers of the acute phase response can be used to indicate the presence of infection and should be considered in the interpretation of results." (PMID 30642010, 2019). "Inflammatory and infection marker levels (such as leucocyte count, C-reactive protein (CRP) and procalcitonin (PCT)) were shown to be increased in surgical and septic patients." (PMID 30701381, 2019). "On comparing CRP with ESR, it was found that CRP had a slightly higher AUC for infection (AUC 0.617, 95% CI = 0.601 to 0.632 versus 0.589, 95% CI = 0.574 to 0.603, P<0.001)." (PMID 31208975, 2019). "We modelled infection this way, because the relationship between CRP and the leukocyte count appears hard to predict: at least in our data, elevated CRP seems to be associated with both increased and decreased leukocyte counts, with no apparent pattern." (PMID 31792398, 2019). "Our results found the accuracy of serological tests, including ESR, CRP and IL-6, was poor in predicting persisting infection before second-stage prostheses implantation, which was similar with previous studies on the two-stage exchange arthroplasty of PJI." (PMID 31159792, 2019). "For example, in the patients with organ dysfunction in the ICU, serum IL-6 levels had the highest diagnostic value for infection among IL-6, PCT, presepsin, and CRP levels." (PMID 31261907, 2019). "Four days after infection, CRP, HP, and ceruloplasmin were elevated but returned to base-line levels up until 3 weeks after infection." (PMID 31001544, 2019). "One controlling factor is that of C-reactive protein (CRP) which is an acute phase protein synthesized in the liver in response to infection." (PMID 31447831, 2019). "The increase in the infection marker CRP, the decrease in coagulation factors, and the increase in glucose reflected probably pathophysiological changes due to the infection itself or surgery and fasting." (PMID 31040341, 2019). "A point-of-care test of CRP and Myxovirus resistance protein A (MxA) was used in 54 patients with pharyngitis or LRTIs to determine the etiology of the infection." (PMID 30987144, 2019). "Previous studies investigated the role of CRP, ERS, and neutrophil-to-lymphocyte ratio (NLR) in SLE patients associated with infection." (PMID 31163082, 2019). "In fact, the CRP/albumin ratio has been shown as an independent prognostic marker in patients with infection, malignancy, and other diseases." (PMID 31781024, 2019). "Although the effectiveness of LZD and DAP was equivalent in terms of infection control rates for refractory PJIs with gram-positive pathogens, DAP therapy significantly decreased CRP levels and caused fewer adverse events than LZD treatment." (PMID 31651331, 2019). "Indirect evidence has been presented to show the importance of the PCh-binding property of CRP and subsequent complement activation by CRP-complexes in protection from infection." (PMID 30863393, 2019). "For years it has been regarded merely as a useful biomarker of infection, tissue injury and inflammation, and it was only in the early 80s that the modified isoforms (mCRP) of native CRP (nCRP) appeared." (PMID 31151201, 2019). "Monitoring CRP levels gives important clinical information about the extent of tissue damage and severity of infections." (PMID 31428091, 2019).
infection (continued). "We observed that the serum CRP level increased significantly in response to S. Typhimurium SL1344 infection but decreased in mice that were pretreated with ZS2058 or LGG." (PMID 30842764, 2019). "C-reactive protein (CRP) is an acute-phase protein that increases remarkably during infection, inflammation, and with tissue damage." (PMID 31086534, 2019). "Published studies have described the role of C-reactive protein in the diagnosis of infections, in particular its overuse post-operatively." (PMID 31528337, 2019). "As serum level of CRP is normally less than 1 mg/dl, it can increase up to35-40 mg/dl in response to infection or inflammation." (PMID 30916140, 2019). "CRP is a highly sensitive, acute-phase protein response to immune reaction after tissues injury, damage or infection." (PMID 31043642, 2019). "C-reactive protein (CRP) is an acute-phase protein that serves as an early marker of inflammation or infection." (PMID 30642010, 2019). "Our second model, an extension of the first, incorporates C-reactive protein (CRP) measurements as a surrogate for infections and models the effect of an infection as extra variation in (or discrepancy from) the leukopoiesis model." (PMID 31792398, 2019). "The serum PCT, CRP and LDH levels and positive detection rates of PCT and CRP were significantly higher (P < 0.05 and P < 0.05, respectively) in the infection than in the control groups." (PMID 30976022, 2019). "It has been observed that after any injury which is acute and also in the setting of inflammation or infection, the synthesis and secretion of C-reactive protein (CRP) rises within a few hours." (PMID 31065202, 2019). "CRP is an acute phase reactant produced by hepatocyte-derived IL-6-dependent biosynthesis in inflammatory conditions, particularly in response to infection." (PMID 31781117, 2019). "This makes sense also from a medical point of view, since CRP is one of the most common indicators of systemic inflammation and is often increased due to infection." (PMID 30915154, 2019). "The presence of infection markers for the species can function as a transcriptional stimulus in combination with other factors to increase CRP secretion in valvulopathy patients." (PMID 30804931, 2019). "Most importantly, it was a more sensitive indicator to distinguish between viral and bacterial cause of SIRS in children ≤12 months of age than standard infection prediction markers like WBC, CRP, or neutrophil count." (PMID 30974881, 2019). "Elevations in baseline CRP level have been used to determine infection and tissue damage and to monitor progression of chronic diseases." (PMID 31346213, 2019). "Clinical serum canine CRP (c-CRP) measurement has been performed for over 30 years, and increased serum c-CRP concentrations are known to occur with several types of infection." (PMID 31262326, 2019). "A PCh-independent mechanism for anti-pneumococcal function of CRP has been proposed along with an explanation for the inability of CRP to be protective against late stage infection." (PMID 30863393, 2019). "C-reactive protein is often thought to be superior for infections, rising more rapidly than the other two tests in response to inflammation." (PMID 31208975, 2019). "CRP is a typical acute-phase reaction protein that abnormally increases under stress conditions, such as infection and tissue damage." (PMID 33817135, 2019). "WBC elevation of > 11 × 109/L was present in 26.0%, and CRP > 50 mg/L was seen in 20.2%, indicating severe infection." (PMID 30606164, 2019). "Consistent with this supposition, experimental and clinical investigations have revealed that high levels of cytokines, such as CRP, decreased circulating cholesterol levels during severe infection." (PMID 31086028, 2019). "In pigs experimentally infected with A.pp., already in the early stage 68 h after infection, an increase in CRP was observed." (PMID 31001544, 2019).
infection (continued). "C-reactive protein (CRP) is an early predictor of postoperative infection and has been shown to correlate with AL." (PMID 30710314, 2019). "Typically, the presence of CRP is detected 12–24 h after the onset of an infection and peak concentration rises 1000-fold and remains elevated up to 3–7 days." (PMID 33117982, 2019). "In surgery, the diagnosis of infection is reliant on infection markers, including C-reactive protein, white cell count, and temperature." (PMID 30445453, 2019). "In the hemolymph of horseshoe crab, Carcinoscorpius rotundicauda, CRP was identified as the major LPS-binding protein in infections with Pseudomonas aeruginosa." (PMID 30863393, 2019). "The management of infection was further assessed by measuring CRP levels in the serum to assess innate immune response and the onset of inflammation." (PMID 30813284, 2019). "In post-operative patients C-reactive protein levels can become elevated in response to the trauma of the surgery, and as such the utility of using this marker as a specific marker of infection is inappropriate." (PMID 31528337, 2019). "Variables include underlying health conditions at recruitment, gestational age, iron intake, infection, pregnancy complications, and CRP concentration, and used as covariables in the different GLM." (PMID 30909605, 2019). "In our dataset, 65% of the patients have at least one infection during their treatment (by counting patients who have at least one CRP measurement greater than or equal to 10 mg/L), highlighting the prevalence of infections in MT." (PMID 31792398, 2019). "A randomized controlled trial has also proved the significantly predictive value of CRP for surgical site infection." (PMID 31533682, 2019). "A recent study reported that serum IL-6 levels had the highest diagnostic value for infection in patients with organ dysfunction compared with PCT and CRP levels." (PMID 31718563, 2019). "In the low-phytate bread group three subjects had CRP > 5 mg/L, and another three subjects in the high-phytate bread group gave positive answers regarding signs of infection or inflammation." (PMID 29796932, 2019). "Factors associated with increased fatality rates in our patients were CRP and duration of hospitalization, while guided antibiotics during hospitalization for the infection episode decreased mortality." (PMID 31438593, 2019). "The combined detection of PCT, CRP and LDH is of high diagnostic value in identifying paediatric malignant solid tumour concurrently with infection and tumour progression and is helpful in the early detection of tumour conditions." (PMID 30976022, 2019). "Alisk was able to prevent CRP production, which is an acute inflammatory protein that increases up to 1,000-fold at sites of infection or inflammation." (PMID 31333451, 2019). "CRP, one of the prototypic molecules of the pentraxin family, is a systemic biomarker of inflammation widely used in the clinic to monitor infections and inflammatory conditions." (PMID 31057548, 2019). "CRP is produced by hepatocytes as a response to infection or tissue damage, mainly in response to the proinflammatory cytokine IL-6." (PMID 31428091, 2019). "Systemic inflammation is characterized by increased inflammatory cytokines (e.g., interleukin-1β (IL-1β), IL-6), proteins (e.g., C-reactive protein (CRP)) and other immunologically active peptides generated at the site of infection." (PMID 31449973, 2019). "The readmitted and single-admission patients in our study were statistically similar in patient and infection characteristics: age, sex, site of infection, presenting, and discharge CRP levels." (PMID 31850363, 2019). "While CRP is an acute-phase protein that serves as an early marker of inflammation or infection, there are significant pitfalls in the use of this biomarker in chronic inflammatory diseases." (PMID 31336842, 2019).
infection (continued). "CRP is persistently produced during infection in the acute phase response via tumor necrosis factor α (TNF- α), interleukin -1β (IL 1 β) and IL-6." (PMID 31856765, 2019). "CRP had the highest overall AUC, largely because of marginally superior performance in infection (AUC CRP 0.617, versus ESR 0.589, P<0.001)." (PMID 31208975, 2019). "Revision surgery was conducted and drug withdrawal when infection indexes, such as C-reactive protein (CRP) and erythrocyte sedimentation rate (ESR) returned to normal." (PMID 30185176, 2018). "The level of CRP (C-reactive protein) in plasma increases greatly during acute phase response to tissue injury, infection, or other inflammatory stimuli." (PMID 30567490, 2018). "The CRP level reflects a complex interaction of stressful conditions such as surgical invasiveness and infection sign." (PMID 29495423, 2018). "Measurement of the concentrations of CRP and procalcitonin thus aids the diagnosis of infection, but has low accuracy for predicting survival." (PMID 30400775, 2018). "Nevertheless, in these two cases gastrointestinal symptoms and the severity of the infection (duration of diarrhoea, number of stools per a day, average CRP serum concentrations) was milder during this method of prophylaxis." (PMID 30355985, 2018). "This study evaluated the feasibility of maternal C-reactive protein (CRP) in amniotic fluid (AF) as a predictor of post-partum infection in women who undergo emergency or elective caesarean section (CS)." (PMID 29686267, 2018). "Key areas of inflammation and host responses to infection mediated by CRP include the complement pathway, apoptosis, phagocytosis, NO release, and cytokine production." (PMID 29706967, 2018). "At ROS, the median CRP in the infection persistence group of 1.10 mg/dl (0.87–1.69) was also significantly higher (p = 0.013) than in the infection eradication group with a median CRP of 0.50 mg/dl (0.62–1.12)." (PMID 29321073, 2018). "Subclinical infection (CRP ≥5 mg/L) was found to be present in 52.1% of the women (95% CI: 48.0–56.0)." (PMID 30205601, 2018). "At day 5, the median serum CRP was higher during MARV/Ang infection (n = 6) at 27.00 mg/dL (25th, 75th percentiles: 23.00, 30.00) than during MARV/MtE-Mus infection (n = 22) at 2.00 mg/dL (25th, 75th percentiles: 0.00, 3.00)." (PMID 30469360, 2018). "In dogs that developed post-surgical infections, a deviation in form of significantly higher concentrations of CRP and SAA were observed at day 6, compared to un-complicated cases." (PMID 29784055, 2018). "In fact, all infections, stress reactions, autoimmunity and tumor disease can contribute to the increase in serum CRP values." (PMID 30285748, 2018). "Although CRP has been used as a biomarker of infection, inflammation and tissue damage, multiple sequential measurements of CRP close together in time are essential for the understanding of its behaviour as a function of time." (PMID 30097610, 2018). "Further studies are needed to expand on these emerging findings and to fully characterize the differential roles that each CRP isoform plays at sites of local inflammation and infection." (PMID 29706967, 2018). "In response to inflammation, cell damage, or tissue injury, plasma CRP level can rapidly and dramatically increase, which has been used as a marker to monitor infections and many destructive/inflammatory conditions." (PMID 30416990, 2018). "Kingsley and Jones stated that CRP increases during infection in response to monocytic mediators such as IL-1 and IL-6 and that it has a stable decay rate." (PMID 29706967, 2018). "The cut-off value for C-reactive protein for ascitic fluid infection was 7.2 with sensitivity 73% and specificity of 71%." (PMID 30289914, 2018). "CRP is produced as a homopentameric protein, termed native CRP (nCRP), which can irreversibly dissociate at sites of inflammation and infection into five separate monomers, termed monomeric CRP (mCRP)." (PMID 29706967, 2018).
infection (continued). "General signs of infection such as fever or elevated CRP values were found in only half of the patients." (PMID 29801466, 2018). "They discovered that mean CRP levels in a spreading infection were higher than those in other colonized, critically colonized, and locally infected groups." (PMID 29706967, 2018). "The level of C-reactive protein (CRP) is also very low in serum of healthy individuals like PCT but increases in various conditions like infections, malignancies, and autoimmune disorders." (PMID 30675399, 2018). "C-reactive protein can mediate host responses to Staphylococcus aureus including some protective function against infection and an increase in phagocytosis of this pathogen." (PMID 29706967, 2018). "C-reactive protein (CRP) is an acute-phase protein that is produced following stimulation by various cytokines in response to infection, ischemia, trauma, and other inflammatory conditions." (PMID 30297655, 2018). "We found statistically significant differences in median CRP and procalcitonin concentrations between the three infection groups, but there was marked overlap in distributions." (PMID 30107791, 2018). "CRP and procalcitonin cut-offs with sensitivities of ≥90% were found for all three target infection pairs, but corresponding specificities were low." (PMID 30107791, 2018). "Serum concentrations of inflammatory markers, such as interleukin-6 (IL-6) and C-reactive protein (CRP), increase transiently then return to baseline after the infection subsides." (PMID 29198208, 2018). "They reported that NLR had higher prognostic accuracy as compared with traditional infection markers such as CRP neutrophil count and white blood cell (WBC) count." (PMID 30234089, 2018). "The range of CRP levels at enrollment was wide, and we were unable to adjust for confounding factors, such as subclinical infection." (PMID 30114262, 2018). "Infection parameters such as CRP and WBC were higher in AA and PA in our study compared to the nonspecific abdominal pain groups." (PMID 30345115, 2018). "Newer proposed algorithms for assessment of fever with no focus have tended to relegate this parameter in favour of other markers of infection, such as CRP and procalcitonin." (PMID 29655624, 2018). "In our series, patients with concurrent infection presented higher CRP levels at baseline, as well as 48 hours after initial treatment." (PMID 30332473, 2018). "White blood count (WBC), neutrophil proportion, and C-reactive protein (CRP) were used as indicators for inflammation/infection in patients." (PMID 29736152, 2018). "Infection index such as C-reactive protein, procalcitonin and leukocyte count was comparable between these two groups." (PMID 29343867, 2018). "In the 210 particpants with single infections the differences in median CRP and procalcitonin concentrations between the three infections were statistically significant, but distributions overlapped considerably." (PMID 30107791, 2018). "After exclusion of patients with an infection before or on day of admission to ICU, the AUC of suPAR for predicting an infection later was 0.62 (95% CI 0.43–0.80) compared to 0.50 (95% CI 0.29–0.71) for CRP." (PMID 30071826, 2018). "The severity of the infection correlates with the CRP level, and the CRP response was shown to be pathogen-dependent." (PMID 29986441, 2018). "The study concluded that the ability of CRP to protect against infection lies in its ability to bind to pneumococcal polysaccharide C in the bacterial cell wall." (PMID 29706967, 2018). "In summary, evidence shows that CRP is not only a marker of infection and inflammation but that CRP also has a protective role against bacterial infections, principally through the activation of complement and subsequent opsonization of pathogens." (PMID 29706967, 2018). "Serum erythrocyte sedimentation rate (ESR) and C-reactive protein (CRP) have been generally used as a screening test for infection because of their simplicity and cost-effectiveness." (PMID 29439725, 2018).